CD80 (CD80 molecule)
Diseases named in the same sentence as CD80 in open-access papers (continued):
Sharing a sentence is not in itself a finding about the gene and the disease.
tumor (continued). "It is possible downregulated CD80 and CD86 expression in large A20 tumors is preventing the sustained CD28 signaling required for an effective adaptive anti-tumor response." (PMID 37016127, 2023). "This can lead to an enhanced PD-L1/CD80 cis-heterodimerization that, by preserving the ability of CD80 to activate CD28, can sustain the functionality of intra-tumor CD28+ T cells." (PMID 37898752, 2023). "Consistent with the in vitro results, MC38‐tumor‐infiltrating cDC1 also showed upregulated CD40, CD80, CD86, and MHC‐II expression after RA treatment." (PMID 36876644, 2023). "For example, CTLA-4 expressed on tumor-infiltrating Treg cells (TI-Tregs) can bind to CD80/86 with higher affinity than CD28, impairing the maturation of APCs and costimulatory signals to further hinder the activation of anti-tumor CD4+ and CD8+ T cells." (PMID 39872303, 2023). "CTLA-4 blockade, i.e., the use of antagonist antibodies preventing CTLA-4 engagement by the natural ligands CD80 (B7.1) and CD86 (B7.2), was soon explored as a therapeutic target in tumor models by Allison." (PMID 36831435, 2023). "The percentage of IRF8+ M-MDSC and TAMs and the expression of CD80 and CD86 in TAMs was increased in Pdcd1f/fLysMCre tumor-bearing mice compared to Pdcd1f/f tumor-bearing mice." (PMID 36581713, 2023). "Recurrent HCC tumor cells interact with cDC2/LAMP3+ DCs via CD274/CD80 and CTLA4/CD80, leading to the formation of clusters around DCs and subsequently reducing antigen presentation and T cell activation efficiency." (PMID 38012715, 2023). "Tumor cells target inhibitory receptors of effector and cytotoxic T cells such as PD-1 and the cytotoxic CTLA-4 by their ligand PD-L1/PD-L2 and CD80 on their surface." (PMID 36816749, 2023). "RA‐treated B16‐OVA tumor cells markedly increased the surface expression of activation markers, including CD40, CD80, CD86, MHC‐I, and MHC‐II on BMDCs." (PMID 36876644, 2023). "Therefore, low expression of CD80 may predict a poor prognosis in tumor patients." (PMID 37476068, 2023). "The binding of CTLA-4 to CD80/CD86 or PD-L1 to PD-1 suppresses T-cell activation, impairing tumour immune response and promoting a tolerogenic tumour microenvironment (TME)." (PMID 37460712, 2023). "We investigated changes in the expression of CD80, CTLA-4 and PD-L1 molecules on tumour cells to understand their response to ICB + PDT." (PMID 37468749, 2023). "The dying tumor cells would release TAAs and T-cell stimulating factors (CRT, CD80, CD86), activating antitumor immune response." (PMID 36759928, 2023). "blocks the interaction between CTLA4 and these ligands, CD80 and CD86, and keeps T cells remain active, which can recognize and kill tumor cells." (PMID 36949947, 2023). "This corresponded with the increased expression of PD-L1 as well as CD80 and CD86 molecules on the AT3OVA tumours." (PMID 37582853, 2023). "The expression level of gene sets related to cytotoxic T cell activation (perforin, granzyme A, and granzyme B), costimulation (CD80 and CD86), and immune checkpoints (LAG3, CTLA4, PD-L1, and PD-1) was found to be increased in the tumor tissue." (PMID 37606040, 2023). "This molecule is expressed on tumour cells and competes with CD28 in binding to CD80 and CD86 ligands on APCs." (PMID 37631324, 2023). "The major tumor-extrinsic mechanism is compensation for PD-L1/PD-1 and/or CTLA-4/CD80/86 blockade through alternate immune checkpoints such as LAG-3, TIM-3, TIGIT, and VISTA." (PMID 37444422, 2023). "CD28 and CTLA4 expressed on T lymphocytes share identical ligands, CD80 and CD86, on tumor cells or antigen-presenting cells." (PMID 36983005, 2023). "For example, the binding of PD-L1 to immune checkpoint PD-1, as well as the binding of CTLA-4 to CD80/CD86 ligands, are key inhibitory checkpoint signals that limit T cell activation and block its action on tumor cells." (PMID 37789267, 2023).
tumor (continued). "The authors reported an increased expression of CD80 and CD86, meaning an increase in DC maturation, a tumor-inhibiting effect (tumor volume ≈ 0 mm3), and higher levels of INF-γ, TNF-α and IL-6." (PMID 37238966, 2023). "MHCI (H2KB and H2DB), MHCII, CD80, CD86 and PD-L1 expression on the AT3OVA tumours were all significantly increased in response to combined inhibitor treatment compared with vehicle controls." (PMID 37582853, 2023). "Panobinostat also upregulated expression of the activating ligands CD80, CD86, and Nectin-2 in tumor cells, promoting NK cell cytolytic effect." (PMID 37090711, 2023). "Redaporfin-PDT stimulates the expression of CD80 in CT26, B16F10 and 4T1 tumour cells and makes them more immunogenic." (PMID 37468749, 2023). "As expected, DOX@3D-MPs treatment remarkably increased the amounts of CD11c+CD80+CD86+ and CD11c+MHC-II+ cells in tumor tissues, revealing that DOX@3D-MPs efficiently promoted intratumor DC maturation." (PMID 37875473, 2023). "Although CD80 and CD86 were highly expressed in multiple tumor-infiltrating lymphocytes, the lower proportions of tumor-infiltrating lymphocytes in the CT26 tumors as compared with the Hepa1-6 tumors made APC-mediated T cell activation less convenient." (PMID 37891570, 2023). "In contrast, M2 macrophages, which have elevated expression of CD206 and reduced expression of CD80 and CD86, promote tissue repair and tumor cell proliferation and suppress antitumor immunity." (PMID 36442099, 2022). "The immunofluorescence intensity of CD80+F4/80+ cell in the center and periphery of B16F10 tumor tissue after PQ/PB-Gel treatment was significantly higher than that of untreated group." (PMID 35832081, 2022). "Such tumor antigen-specific immune responses triggered by the nanoparticles coated with OVA and CD80-overexpressed cancer cell membranes significantly inhibited tumor growth in vivo." (PMID 35216342, 2022). "M2 GAMs express high levels of CD163, CD206, and CD14; low levels of CD80 and MHC II; and secrete molecules that mediate immunosuppression and promote tumor progression." (PMID 36466873, 2022). "M1 macrophages (CD86+ and CD80+) release pro-inflammatory cytokines (e.g., IL-6, IL-12, TNF-α) to play an anti-tumor role, while M2 macrophages (CD206+) release pro-tumor cytokines (e.g., IL-4, IL-10, IL-13) to promote tumor progression and metastasis." (PMID 35432300, 2022). "Cluster #4 presented with the most abundant expression of maturation markers including LAMP3, CD80, CD40, the migration marker CCR7, and overexpressed the tumor Secretory cDC2 signature, thus #4 was labeled mmDC." (PMID 35418195, 2022). "Studies have shown that the addition of the costimulatory molecules CD80 or 4-1BBL to CAR19-BBζ or CAR19-28z T cells, respectively, enhanced CAR T-cell persistence and tumor clearance in a mouse model of ALL." (PMID 36922932, 2022). "As expected, the “aCD47/Ce6@PPG + L” group exhibited the strongest ability to upregulate M1-like TAMs (CD80+CD11b+F4/80+) and downregulate M2-like TAMs (CD206+CD11b+F4/80+) in tumor tissues." (PMID 35931666, 2022). "The effector memory of CD4+ T cells and the amount and CD80 expression of macrophages were enhanced in both the TC1 and C3PQ tumor models." (PMID 35356198, 2022). "The cell suspension was prepared to analyze the populations of CD86+CD80+ and CD8+CD45+ cells in tumor tissues." (PMID 36131787, 2022). "Our results showed that DCs cocultured with Smad4KO tumor cells showed higher levels of CD80+ and CD86+ cells than those cocultured with WT tumor cells." (PMID 35064757, 2022). "We demonstrated that P4HA1 expression was positively correlated with the expression of TNFSF15, CD80, VTCN1, TNFSF18, and CD200R1 in multiple tumor types but negatively correlated with the expression of CD40LG and CD244." (PMID 35812752, 2022).
tumor (continued). "PD-1, which binds to PD-L1, also known as CD274, or to PD-L2/CD273, is a peripheral immune checkpoint of immune, tumor, and stromal cells, whereas CTLA-4 binds to CD80/CD86, also known as B7-1/B7-2 co-stimulatory receptors, on antigen-presenting cells (APCs)." (PMID 35159208, 2022). "Mature DCs (mDCs) express MHC II, costimulatory molecules CD80 and CD86 and secrete pro-inflammatory cytokines that prime T cells to regress the tumour and metastases." (PMID 36140243, 2022). "We found that CSF-1R was significantly correlated with tumor-related immunosuppressive molecules including PDCD1, CTLA4, CD80, CD86, HAVCR2, etc.." (PMID 35444953, 2022). "Co-stimulatory ICMs CD28, CD80 and CD40LG are secondary signal molecules in the T lymphocyte activation, which activate patients’ anti-tumor immune responses, leading to increased efficacy of cancer immunotherapy." (PMID 35953696, 2022). "Specifically, by expressing MHC II, CD74, CD80/CD86 and CD11c, they function as tumor antigen-presenting cells, and activate T cells, leading to tumor cell death and clearance." (PMID 36411434, 2022). "In summary, the [CD80/OVA]NPs can act as artificial APCs to directly stimulate T cells, thus inducing anti‐tumor immune response to inhibit tumor growth." (PMID 37324583, 2022). "Both TCGA and GEO data showed a good predictive value, and four genes (GIMAP6, CD80, IL16, CCR2) contributed the most to predicting tumor purity." (PMID 35280857, 2022). "The percentage of CD80+ and CD86+ DCs after treated with CM was higher than that treated with DM, demonstrating that the CM carrying tumor antigens played a leading role in FMs‐induced maturation of DCs." (PMID 37324583, 2022). "To validate these findings in vivo, we evaluated the expression levels of CD80, VISTA, LAG-3, SIRP-α and TIM-3 on freshly isolated Ly6C+ monocytes, derived from healthy, Ctrl or anti-PD-L1 mAb treated tumor-bearing mice." (PMID 35493461, 2022). "Next, expression levels of F4/80, CD80, and TNF‐ɑ in the tumor tissues of mice in each group were detected by western blot." (PMID 34994088, 2022). "Nevertheless, upregulation of CD80 and CD86 on tumor cells was observed after treatment with OV-OX40L/IL12 ex vivo or in vivo in our study, suggesting that including some costimulatory ligands is sufficient to jump-start a network of costimulatory signals." (PMID 35715953, 2022). "Upon activation through Toll-like receptors (TLRs), DCs upregulate MHC and co-stimulatory molecules, including CD40 and CD80/CD86, all of which interact with T cells to promote a proinflammatory or anti-tumor response." (PMID 36248881, 2022). "Targeting CTLA-4 to treat tumours requires blocking the interaction between CTLA-4 and its CD80/CD86 ligand." (PMID 36195696, 2022). "In vivo data showed that oxaliplatin suppressed tumor growth and increased the populations of CD86+CD80+ and CD8+CD45+ cells in the tumor tissues." (PMID 36131787, 2022). "Starting 2 d after treatment, there was a significant increase in the proportion of converted tumor-migratory CD103+ cDC1s co-expressing CD40 and CD80 in the radiation-treated group compared with untreated controls." (PMID 35487695, 2022). "On the contrary, cytotoxic T-lymphocyte-associated protein 4 (CTLA4) is a negative regulatory inducible receptor for CD80/CD86 and has inhibitory effects on T cell responses, leading to T cell attenuation and tumor cell immune evasion." (PMID 35656508, 2022). "CTLA-4 binds to its ligands B7-1 (CD80) and B7-2 (CD86) to generate inhibitory signals that suppress T cell activation and cytokine production and protect tumor cells from T cell attack." (PMID 36532071, 2022). "Costimulatory molecule expression (CD80 and CD40L) in the tumor is significantly correlated with overall survival." (PMID 36073543, 2022). "Tumor treatment with decitabine also resulted in increased levels of MHC and costimulatory molecules (CD80, CD86, and CD40) essential for DC antigen presentation function." (PMID 35992806, 2022).
tumor (continued). "Tumor immune cells (PTPRC/CD45+) also consisted of B cells (MS4A1/CD20+), plasma cells (XBP1+), macrophages (CD14+), dendritic cells (CD80+, CD86+), and mast cells (TPSAB1+)." (PMID 35742914, 2022). "It has been proposed that CTLA-4 in TEV acts as a scavenger for the CD80/CD86 pro-apoptotic ligands, thereby protecting tumour cells." (PMID 36011012, 2022). "Anti-CTLA-4 antibodies boost T cell activation and the following anti-tumor response by blocking the interaction of CTLA-4 and CD80/86 and inducing immune responses to weak tumor antigens." (PMID 35152908, 2022). "Tumor cell co-stimulatory or co-repressor signaling, involving genes such as CD28, CD80, CD86 and CTLA4, plays a critical role in regulating cell proliferation, differentiation and cytokine secretion." (PMID 36465397, 2022). "The results showed that the levels of F4/80, CD80, and TNF‐ɑ protein in tumor tissues of the Nr‐CWS treatment group were higher than those in the PBS group." (PMID 34994088, 2022). "Previous studies have demonstrated that up-regulation of CD80 and CD86 in the tumor vaccine systems can successfully improve the immunogenicity of vaccines due to the effect of costimulatory CD80 and CD86 molecules on tumor immunity." (PMID 36466863, 2022). "We defined several immune subsets from the spleen and tumor by using CD8b, Thy1.1, PD-1, NK1.1, CD11b, CD11c, MHC-II, CD80, Ly6G, Ly6C, F4/80, and CD206 antibodies." (PMID 36497152, 2022). "Further, PTT with aFn14-PBNP resulted in a unique tumor cellular immunophenotype consisting of thermal dose-dependent enhanced expression of CD137L, CD80, CD86, and CD40." (PMID 35957076, 2022). "Co-culture of the virus-infected cells with TILs, upregulation of MHC I, MHC II, and costimulatory receptors, such as CD80 and CD86 on tumor cells and increased the IFN-γ-secreting cells, leading to delayed tumor growth and improved survival time." (PMID 36389779, 2022). "It promotes tumor growth via angiogenesis and inhibits GADC maturation by downregulating costimulatory factors CD80 and CD86, which are necessary to produce robust anti-tumor immune responses." (PMID 35711434, 2022). "In the tumor, this effect was most prominent in the Flt3L+NDV cohort, with significantly higher expression of activation markers (e.g. MHC I/II, CD80, CD40), particularly in cDC1s, suggesting greater-than-additive effect when combining NDV and Flt3L." (PMID 36418317, 2022). "Dormant tumor cells in the DA1-3b/C3H mouse model of AML evade cytotoxic T-lymphocyte (CTL)-mediated killing because they overexpress PD-L1 (B7-H1) and CD80 (B7-1)." (PMID 33987095, 2021). "Blockade of CTLA4 has been shown to increase the infiltrative T cell and decrease Treg response to tumor cells by allowing the co-stimulatory receptor CD28 to bind CD80 (B7.1) and CD86 (B7.2) expressed on antigen-presenting cells (APC)." (PMID 34976006, 2021). "Among all tested combinations, the triplet of OX40L, CD80 and CD86 mRNA induced the strongest anti-tumor immunity in subcutaneous A20 and CT26 tumor-bearing mice." (PMID 33858437, 2021). "The two most heavily studied checkpoint inhibitor pathways in the tumor ablation field are CTLA-4 to CD80/86, blocking the normal co-stimulatory role of CD80/86 in T cell activation, and PD-1 to PDL1/2." (PMID 34136405, 2021). "The AAA-CD4+ T cells also recruited significantly more host DCs and macrophages into the tumor, which expressed high levels of antigen-presenting molecules (MHC class II), co-stimulatory molecules (e.g., CD80 and CD86), and cytokines (IL-12 and IL-23)." (PMID 34625113, 2021). "Low levels of CD80 expression serve as a mechanism of tumor escape from immune surveillance due to a higher affinity and, therefore, preferential binding of CTLA-4 to CD80 compared with that for CD28." (PMID 33923750, 2021).
tumor (continued). "M1 macrophages, highly expressed major histocompatibility complex class II, CD68 labeling and CD80/CD86 costimulatory molecules, located within tumors are thought to induce tumor suppression by activating anti-tumor immunity." (PMID 35284334, 2021). "We observed that ILT4 knockdown in tumor cells decreased M2-like markers, including CD163, CD206, IL-10, and Arginase 1 but increased M1-like markers including CD80, CD86, IL-12, and TNFαin TAMs." (PMID 33537094, 2021). "We also noted a significant increase in the M1-like to M2-like TAM ratio (defined as the ratio between CD80+ and CD206+ TAMs), indicating an increased presence of anti-tumor M1-like TAMs." (PMID 33747968, 2021). "However, the role of CD80 may differ in various tumor types." (PMID 33923750, 2021). "We found that tumor-infiltrating CD33high cells showed high gene expression levels of CD36, CD14, FUT4 (CD15), CD80, CD86, CSF1R and immune checkpoint ligand genes including CD274 (PD-L1), LGALS9 (galectin-9), PVR and VSIR." (PMID 33000418, 2021). "CTLA-4 outcompetes the co-stimulatory molecule CD28 for binding to B7-1/CD80 or B7-2/CD86 expressed on the surface of antigen presenting cells, including tumour infiltrating dendritic cells." (PMID 33995362, 2021). "Differential analysis of tumour compartments indicated the enrichment of GZMA, STING and fibronectin in responsive patients, while CD80 levels were higher within refractory tumours." (PMID 35083152, 2021). "On the other hand, serum butyrate levels limit the anti-tumor efficacy of anti-CTLA4 therapy in metastatic melanoma by restraining the up-regulation of CD80/CD86 on dendritic cells and ICOS on T cells, accumulation of tumor-specific T cells and memory T cells." (PMID 33708214, 2021). "The maturation status of TIDCs, hence the expression of costimulatory molecules like CD80 and CD86, seems to be determined by the tumor entity." (PMID 33141285, 2021). "The T cell inflamed tumor biomarker CD274 (PD-L1) was significantly upregulated in the LsS4D in addition to BATF3, CD247 (CD3ζ), CD80 among others." (PMID 33776991, 2021). "Treg cells has the ability to limit the function of antigen presenting cells by CTLA-4 dependent downregulation of CD80 and CD86 expressions, thereby evading tumor antigen presentation and tumor-specific T cell activation." (PMID 34012451, 2021). "The number of tumor-infiltrating DCs, mature DCs expressing major histocompatibility complex (MHC) class II and activated CD103+ DCs with high expression of CD80 was identical between hIL-7/mIL-12-VV- and mIL-12-VV-treated tumors." (PMID 33909103, 2021). "Tumor cells within defined branch I in different tumors have upregulation of CTLA4 and CD80, indicating a better response to anti-CTLA4 therapy." (PMID 33971970, 2021). "The tumour cells can escape from the killing of T cells by activation of PD‐1/PD‐L1, CTLA4/CD80/CD86 and other immune checkpoints." (PMID 33325636, 2021). "PD-1 and CTLA-4 binding to their ligands, respectively PD-L1 and CD80/CD86, expressed by tumor and other cells, leads to functional exhaustion and impairs anti-tumor immunity." (PMID 34370787, 2021). "CTLA-4 binds to its ligands CD80 (B7-1) and CD86 (B7-2) and inhibits T-cell activation, negatively regulates T-cell functions, and mediates tumor immunosuppression." (PMID 34943817, 2021). "We then examined the changes in M2-like TAM markers (CD163, CD206, CD209, IL-10 and Arginase 1) and M1-like TAM markers (CD80, CD86, IL-12, and TNFα) induced by CM from ILT4-downregulated tumor cells." (PMID 33537094, 2021). "Further, A20 expressing 4-1BBL in combination with CD80 and CD86 have been observed to be highly immunogenic, thereby inducing durable anti-tumor responses." (PMID 33666760, 2021). "Interactions between CTLA-4 and its ligands, CD80 and CD86, inhibit T cell activity and consequently induce tumor progression." (PMID 34298809, 2021).